IL10 (interleukin 10)
Diseases named in the same sentence as IL10 in open-access papers (continued):
Sharing a sentence is not in itself a finding about the gene and the disease.
tumor (6,614 papers, 1994 to 2026). "Specifically, the activation of the MEK-ERK-AP1 pathway by mutated KRAS induces tumor cells to secrete interleukin-10 (IL-10) and transforming growth factor-β1 (TGF-β1)." (PMID 41362725, 2026). "Tumor-associated neutrophils and MDSCs can release IL-10 or Arg-1, which also influence macrophages toward M2." (PMID 41597210, 2026). "ALG1 overexpression altered tumour microenvironmentsignalling, changing IL10 and CYPA pathways associated with immune suppression." (PMID 42002825, 2026). "Engineered Salmonella enterica strain can inhibit the proliferation and metastasis of various tumors by inducing tumor‐associated macrophages to secrete IL‐10 and stimulating CD8+ T cells, while evading phagocytosis by tumor‐associated neutrophils." (PMID 41574027, 2026). "The multifaceted role of sustained IL-10 in simultaneously activating and expanding cytotoxic tumor-specific CD8+ T cells while suppressing tumor-associated inflammation has positioned it as a cytokine of significant clinical interest in cancer immunotherapy." (PMID 40149345, 2025). "IL-12, IL-2, and IFN-γ promote Th1 differentiation, which supports antitumor immunity, whereas IL-4, IL-5, and IL-10 drive Th2 differentiation, which is associated with tumor growth and immune suppression." (PMID 40429961, 2025). "Lactate accumulation promotes polarization of tumor-associated macrophages toward an M2 phenotype, leading them to secrete inhibitory cytokines (e.g., interleukin-10) and express PD-L1, which in turn suppresses T-cell function." (PMID 40672941, 2025). "At the same time, tumor cells can modulate the immune microenvironment by producing IL-10, causing the immune system to shift towards a suppressed state, thereby promoting immune escape of the tumor." (PMID 40045277, 2025). "Through IL‐10Rhi, IL‐10 suppresses tumor‐associated neutrophil phagocytosis via signal transducer and activator of transcription 3 (STAT3) signaling, ensuring bacterial survival." (PMID 40878391, 2025). "Lastly, evaluating the relationship between systemic cytokines and the tumor microenvironment revealed a significant association between IL‐10 and CD163+M2‐TAM expression (p < 0.05)." (PMID 41263059, 2025). "High MiCU1/2 expression correlates with increased infiltration of M2-type tumor-associated macrophages (TAMs), which promote tumor progression, angiogenesis, and immune evasion via immunosuppressive cytokines like IL-10 and TGF-β." (PMID 40867511, 2025). "Tumor RNA-seq analyses across multiple DLBCL cohorts consistently demonstrated that elevated IL-10/IL-6 expression ratios were associated with poorer clinical outcomes." (PMID 40881684, 2025). "The macrophage receptor with collagenous structure (MARCO), found on tumor-associated macrophages (TAMs), has been shown to stimulate Treg proliferation and IL-10 production in NSCLC." (PMID 41378295, 2025). "For example, immunosuppressive factors in the TME (such as TGF-β and IL-10), hypoxia, and tumor-associated fibroblasts (CAFs) collectively reduce the survival and cytotoxicity of CAR-T cells." (PMID 40264788, 2025). "IL-10 in NSCLC has been linked to tumor tolerance, larger tumor size, and regulatory T-cell infiltration, but its overall expression remains suppressed compared to surrounding tissue." (PMID 41020868, 2025). "This is evidenced by the dose-dependent reduction in the serum levels of the IL-10 (M2-specific cytokines) and Arg-1 (hallmark marker for M2 macrophages) following L-K5 treatment, which correlated with inhibited tumor growth and reduced liver metastasis." (PMID 40943546, 2025). "First, we found that age at diagnosis differed among patients carrying genetic variants of TLR3 and IL10, suggesting a role of these pathways in the spontaneous, therapy-independent anti-tumor immune response." (PMID 41469691, 2025). "Higher levels of MDSCs in HCC tumor-bearing mice are associated with increased IL-10 expression, reduced IL-12 production by DCs, and lower T cell stimulatory activity." (PMID 40432108, 2025).
tumor (continued). "Among various myeloid subsets, M2 macrophages, the main population of tumor-associated macrophages (TAMs), exhibit immune suppressive functions characterized, for example, by their local production of IL-10 or TGF-β." (PMID 40860824, 2025). "The mechanism behind IL-10’s association with worse outcomes lies in its ability to create a tumor-permissive environment." (PMID 41007766, 2025). "In particular, high levels of IL-10 are directly involved in the differentiation of M2-type tumor-associated macrophages (TAMs) which, in turn, secrete IL-10, increasing the anti-inflammatory process capable of bypassing activated immune defenses." (PMID 40573308, 2025). "Th2 cells, traditionally associated with the secretion of IL-4, IL-6, and IL-10, play a role in the tumor microenvironment, as these cytokines activate M2 macrophages." (PMID 40136347, 2025). "On the other hand, M2 polarization results in the formation of tumor-associated macrophages (TAMs) driven by the predominance of IL-4, IL-10, and IL-13 production from activated Th2 cells." (PMID 40055269, 2025). "Research indicates that certain tumor-associated microbes create an immunosuppressive microenvironment by secreting metabolic byproducts or inducing immunosuppressive cytokines (such as IL-10 and TGF-β), thereby inhibiting T cell activation and proliferation." (PMID 41450920, 2025). "In contrast, IL‐10 and IL‐13, which are associated with the suppression of anti‐tumor immune function, showed statistically significant decreases." (PMID 39815665, 2025). "In this context, polymorphisms in the IL10 gene—which encodes a key cytokine involved in immunomodulatory processes—have been associated with variable tumor susceptibility." (PMID 40761554, 2025). "M2 tumor-associated macrophages (TAMs) promote immune evasion by secreting immunosuppressive cytokines such as IL-10 and TGF-β, which inhibit T-cell activation and promote regulatory T cells (Tregs)." (PMID 41044153, 2025). "Tumor-associated macrophages (TAMs), typically polarized to an M2-like phenotype, secrete IL-10 and TGF-β, which sustain immunosuppression." (PMID 40297580, 2025). "Tumour-associated macrophages (TAMs), often polarised to an immunosuppressive M2 phenotype by NF-κB signalling, secrete cytokines such as interleukin-10 (IL-10) and transforming growth factor-beta (TGF-β)." (PMID 40650758, 2025). "Tumor-associated macrophages (TAMs), often polarized toward the M2 phenotype, promote tumor growth by secreting anti-inflammatory cytokines (e.g., IL-10, TGF-β) and pro-angiogenic factors (e.g., VEGF), facilitating immune evasion, angiogenesis, and metastasis." (PMID 40230883, 2025). "M2-type tumor-associated macrophages highly express interleukin-10 and transforming growth factor-β, both of which are associated with tumor-promoting effects." (PMID 40136462, 2025). "Accelerated tumor growth in the Gsdmdfl/fl CD4cre mice was associated with decreased cytokine levels, including IL-2, IL-12, IL-4, and IL-10." (PMID 40759573, 2025). "To assess the PCa tumour microenvironment for impaired immunity, we also performed a pilot RNA-expression analysis for PCa-associated immunological factors (IL1β, IL10, IL18, TNF-α, TLR4, GATA3, CD68)." (PMID 40430084, 2025). "Tumor-associated macrophages secrete immunosuppressive cytokines such as IL-10 and TGF-β, further suppressing anti-tumor immune response." (PMID 41476608, 2025). "IL‐10, secreted by tumor‐associated macrophages, stimulates cancer stem cell‐like characteristics in NSCLC cells via the JAK1/STAT1/NF‐κB/Notch1 pathway." (PMID 41223031, 2025). "Immune-suppressive factors present in the TME, such as TGF-β, IL-10, and tumor-associated macrophages (TAMs), indirectly affect the anti-tumor capacity of CD8+ T cells." (PMID 39995670, 2025). "Suppressive cells in TME – Regulatory T cells (Tregs), myeloid-derived suppressor cells (MDSCs), tumor-associated macrophages (TAMs) secrete IL-10/TGF-β and deplete nutrients (e.g., arginine)." (PMID 41194917, 2025).
tumor (continued). "In contrast, M2 macrophages are associated with immune suppression, tissue remodeling, and tumor progression, secreting factors like IL-10, TGF-β, and VEGF, which promote angiogenesis and evade anti-tumor immunity." (PMID 40242222, 2025). "E5 and E6 concurrently facilitate the recruitment of tumor-associated macrophages (TAMs), which release pro-tumor cytokines (including IL-10, VEGF, and TGF-β) and inhibit anti-tumor immune responses." (PMID 40431173, 2025). "Among the M2-like macrophage-derived factors with a known role in tumor progression, Pdgfc and Il10 were upregulated in Mir34a-deficient macrophages, particularly in the Mrc1+ subtype." (PMID 39425000, 2025). "M2 macrophages, in response to tumor-associated cytokines, lose their antitumor function and instead secrete immunosuppressive factors like IL-10, TGF-β, and IDO, promoting immune evasion." (PMID 40291917, 2025). "This M2-like polarization is associated with cytokine secretion (e.g., TGF-β, IL-10) that fosters immune evasion and promotes tumor growth." (PMID 40433363, 2025). "We also analyzed the expression of M1 markers (IL‐1β, Nos2, TNFα) and M2 markers (Arg‐1, CD206, IL‐10) in tumor‐associated macrophages." (PMID 39791593, 2025). "The role of IL-10 in modulating tumor susceptibility was further demonstrated in squamous skin tumor models." (PMID 40149345, 2025). "IL-10, expressed by tumor-associated macrophages, is another cytokine involved in immune escape mechanisms in several malignant tumors." (PMID 41051603, 2025). "Immunosuppressive cytokines such as IL-4 and IL-10 promote differentiation of monocytes to tumor-associated macrophages and regulatory T cells, thereby inhibiting T-cell effector functions and contributing to a protumorigenic environment." (PMID 40807278, 2025). "Th2 cells that promote tumor development exhibit a regulatory profile associated with high levels of IL-10 and TGF-β secretion." (PMID 39782693, 2025). "In the immune cell differential analysis, macrophages M2 are significantly more prevalent in the high-risk group, potentially facilitating tumor growth by secreting immunosuppressive cytokines, such as IL-10 and TGF-β, which inhibit T cell activity." (PMID 40463372, 2025). "For instance, immunosuppressive cytokines like interleukin-10 and transforming growth factor-β secreted by tumor-associated macrophages (TAMs) promote tumor growth and are associated with poorer outcomes." (PMID 38778609, 2025). "In contrast to CD28 signaling, SLAMF7 engagement reduced IL-10 secretion, a cytokine with well-established immunosuppressive functions, as well as IL-6 levels, which has been implicated in inflammation-driven tumor progression." (PMID 40909279, 2025). "CCL18 also influences DC fate by attracting immature DCs to the tumour niche, where they differentiate into tumour-associated DCs (TADCs), which produce immunosuppressive IL-10 and indoleamine 2,3-dioxygenase (IDO), further expanding Tregs." (PMID 40361472, 2025). "The antitumor or pro-tumor role of IL-10 is linked to the phosphorylation of signal transducer and activator of transcription (STAT) 1 or STAT3." (PMID 41041322, 2025). "Tumor-associated macrophages (TAMs) concurrently assume M2 polarization and suppress autoimmune activity through IL-10." (PMID 40959090, 2025). "M2-type macrophages, which are linked to tumor progression, secrete IL-10 and suppress the Th1 immune response, further inducing tumor invasion and metastasis." (PMID 40933989, 2025). "Polymorphisms in genes encoding cytokines (IL6, TNF, and IL10) and HLA molecules influence the liver’s immunological tolerance and tumor surveillance capacity." (PMID 40869967, 2025). "Tumor-associated macrophages produce large amounts of the immunosuppressive cytokine IL10, which inhibits the cytotoxic activity of Th1 cells, NK cells, and CD8+ T cells against tumor cells." (PMID 41019045, 2025).
tumor (continued). "In colorectal cancer, exosomal miR-1246 promotes mutations in tumor cells, induces M2 macrophage polarization, and remodels the tumor microenvironment by upregulating IL-10, transforming growth factor beta (TGFβ), and matrix metalloproteinase (MMP) expression." (PMID 41502528, 2025). "Tumor-associated macrophages (TAMs) further support tumor progression by producing IL-10, VEGF, and matrix metalloproteinases (MMPs), which promote angiogenesis, extracellular matrix remodeling, and invasion." (PMID 41311372, 2025). "The immunosuppressive cytokines (TGF-β, IL-10) according to the equation model shows that cancer-associated fibroblasts (CAFs) grow based on tumour size (Equation)." (PMID 41463127, 2025). "For instance, tumor-associated macrophages (TAMs) producing IL-10 or TGF-β contribute to immunosuppression, while CD8+ T cells secreting IFN-γ exhibit anti-tumor activity." (PMID 40881677, 2025). "The loss of PI3K activity in tumor-associated macrophages (TAMs) promotes the development of pro-inflammatory mediators while reducing IL-10 and arginase expression, which contribute to immune suppression." (PMID 40507854, 2025). "Given IL-10’s context-dependent role in cancer—exhibiting both tumor-promoting and tumor-suppressive effects, we extend our analysis to explore IL-10 signaling associated genes in HL-60 cells." (PMID 40986633, 2025). "High IL-10 in tumors is associated with nodal metastasis and overall signifies an immune-cold, worse-prognosis tumor profile." (PMID 41007766, 2025). "Contrary to conventional understanding, which typically associates IL‐10 overexpression in the tumor immune microenvironment with immune evasion and immunosuppression, recent studies conducted by Tang Li and colleagues have revealed unexpected findings." (PMID 40855662, 2025). "Upon tumor colonization, the immunogenicity of DB1 activated Toll‐like receptor 4 (TLR4) signaling in tumor‐associated macrophages (TAMs), promoting interleukin‐10 (IL‐10) secretion and reshaping the tumor immune microenvironment." (PMID 40878391, 2025). "In the early stage of tumor development, tumor-infiltrating M1-polarized macrophages usually show a phenotype of high IL-12 and low IL-10 expression, promoting the immune response and causing lysis of tumor cells." (PMID 40129606, 2025). "For instance, tumor-associated macrophages (TAMs) release interleukin-10 (IL-10), which suppresses cytotoxic T-cell antitumor responses." (PMID 41226014, 2025). "IL-10 is mainly secreted from tumor-associated pro- and anti-inflammatory microglia and macrophages (TAMs)." (PMID 40564171, 2025). "In contrast, M2 polarization, associated with tumor promotion, is activated by signals like IL-4, IL-10, and TGF-β, primarily through the JAK/STAT6, PI3K/AKT/mTOR, and TGF-β/SMAD pathways, promoting tissue repair, immune suppression, and angiogenesis." (PMID 40330466, 2025). "Tumor-associated monocytes polarize into pro-tumor M2 macrophages, secreting IL-10 and TGF-β to inhibit antitumor immunity while facilitating angiogenesis and extracellular matrix remodeling." (PMID 40977712, 2025). "While Tregs inhibit anti-tumor immunity through IL-10 and TGF-β, a dominant Th2 response (IL-4, IL-10) is associated with tumor growth." (PMID 41018485, 2025). "M2 macrophages, as the primary expression form of tumor-associated macrophages, promote Th2 cell differentiation through the induction of IL-4, IL-13, and other cytokines and secrete IL-10, TGF-β to suppress inflammatory cytokines." (PMID 39104717, 2024). "In the TME, where chronic inflammation fuels tumor growth, the anti-inflammatory activities of IL-10 have been implicated in harnessing the anti-tumoral functions of CD8+ T cells." (PMID 39281678, 2024). "Specifically, Enterococcus can reside within macrophages and neutrophils, stimulating the secretion of cytokines such as IL-6 and IL-10, which are associated with tumor development and immunosuppression." (PMID 38893183, 2024).
tumor (continued). "This aligns with other studies showing that increased release of IL-10 in OvCa is associated with a highly immunosuppressive environment driving tumor progression with ICI therapy." (PMID 39312740, 2024). "PD1/PD-L1 interaction between tumor cell and T-cells causes T-cell exhaustion and anti-inflammatory interleukin-10 (IL-10) production." (PMID 39343796, 2024). "Serum IL-10 levels have been found to be positively associated with tumor stage and negatively with prognosis in CRC patients." (PMID 38918278, 2024). "Tregs in the tumor produce cytokines such as IL-4, IL-10, and IL-13, which cause monocytes to differentiate into tumor-associated macrophages (TAMs)." (PMID 39253716, 2024). "In the brain TME, astrocytes, and tumor-associated macrophages (TAMs) type 2 (M2) produce IL-10 and transforming growth factor β (TGF-β), which inhibit the effector roles of TAM type 1 (M1) and CTL." (PMID 38994941, 2024). "Tumor-associated macrophages are often polarized to the M2-like type in response to IL-4, IL-10, IL-13, and other cytokines, favoring angiogenesis, dissemination, and immunosuppression." (PMID 39456647, 2024). "Interleukin‐10 (IL‐10) is a regulatory cytokine with low molecular weight, and is associated with (breast) cancer initiation and progression, but the effect of IL10 on (breast) cancer development is complex." (PMID 38711262, 2024). "In the TIME, microglia can acquire an anti-inflammatory phenotype, which is associated with a tumor-promoting effect, and secrete anti-inflammatory cytokines, such as IL-10." (PMID 38750472, 2024). "On the other hand, IgA+ plasma cells turned out to be a source of IL-10 and PD-L1, causing suppression of anti-tumor Th1 cells and CTL." (PMID 38500875, 2024). "M2-polarized, tumor-associated macrophages (TAMs) produce pro-tumorigenic and angiogenic mediators, such as interleukin-8 (IL-8) and IL-10." (PMID 39273558, 2024). "IL-10 has been associated with inhibiting neovascularization and tumor metastasis by downregulating the synthesis of VEGF, IL-1β, TNF-α, IL-6, and MMP-9 in tumor-associated macrophages and natural killer (NK) cell-dependent mechanisms, respectively." (PMID 38672182, 2024). "CmAb-(IL-10) is an anti-EGFR antibody (cetuximab)-based IL-10 ICK which displayed enhanced antitumor responses on an EGFR-positive tumor mouse model associated with a reduced toxicity." (PMID 39204319, 2024). "Infiltration of M2 TAMs and upregulation of IL-10 expression disrupt T-cell function, causing an imbalance in tumor immunity." (PMID 39169402, 2024). "Studies have shown that tumor cells can release cytokines such as IL-6, IL-10 and TGF-B that cause dendritic cells to remain in an immature or immunosuppressive stage." (PMID 39108491, 2024). "Factors associated with the tumor microenvironment (IL-10, IL-6) hinder the differentiation of DCs, decrease their maturation, and suppress T cell activation." (PMID 38426090, 2024). "The secretion of growth factors such as TGF-β and VEGF and cytokines such as CCL2 and IL-10 by tumor cells enables angiogenesis and recruitment of tumor-associated macrophages, promoting tumor growth and metastasis." (PMID 39407505, 2024). "CD155+ tumor-associated macrophages showed an M2 phenotype and higher expression of interleukin (IL)-10 and transforming growth factor (TGF)-β." (PMID 39091493, 2024). "The cytokine IL-10 has been implicated in anti-tumor effects as humans deficient of IL-10 develop tumors spontaneously and at high rates." (PMID 38228372, 2024). "In models of breast cancer, cutaneous squamous cell carcinoma, and lymphoma, IL-10 deficiency correlates with increased tumor burden and impaired immune surveillance, along with elevated rates of CD8+ T cell exhaustion." (PMID 39726592, 2024). "Next, quantitative PCR was performed to evaluate the expression of the pro-tumour TAM-associated genes IL-10, CCL2 and IDO-1, which were all increased in both SKOV-3 and OVCA433 generated TAMs compared to pre-cultured autologous monocytes." (PMID 39763667, 2024).